IGF1 (insulin like growth factor 1)
Diseases named in the same sentence as IGF1 in open-access papers (continued):
Sharing a sentence is not in itself a finding about the gene and the disease.
Hypoglycemia (continued). "NICTH should be considered in non-diabetic patients who have recurrent hypoglycemia along with suppressed serum insulin and IGF-1 levels." (PMID 36211262, 2022). "The ratio of insulin/glucose was 0.62, and the response of cortisol, insulin-like growth factor-1 (IGF-1), and glucagon to hypoglycemia was not significant." (PMID 34032745, 2021). "GHR-KO pigs show important hallmarks of the human disease, including reduced levels of insulin-like growth factor 1 (IGF1) and IGF-binding protein 3 (IGFBP3), increased serum GH concentrations, postnatal growth retardation, juvenile hypoglycemia, and a progressive increase in total body fat." (PMID 33029223, 2020). "Lack of IGF-1 was correlated with a decrease in adipose tissue, lordokyphosis, and severe hypoglycemia." (PMID 33442387, 2020). "Furthermore, Sub mice showed a marked hypoglycemia, reduction of insulin levels, increase in GSK3 activity and elevation of IGF-1 serum levels, as well as low skin surface temperature and body weight." (PMID 31707362, 2019). "Briefly, such dosage is enough to restore normal circulating IGF-1 values without inducing hypoglycemia and any adverse effects." (PMID 28124277, 2017). "Endocrinopathies are known to be associated with 18p deletion syndrome, so initial lab workup was done at birth which demonstrated low insulin-like growth factor-1 (IGF-1) without hypoglycemia and normal thyroid function tests." (PMID 27843654, 2016). "Therefore, we aimed to investigate the occurrence of post-load hypoglycemia by a 2 h OGTT and to assess the utility of IGF-1 serum levels before and after bariatric surgery as a biomarker for post-load hypoglycemia." (PMID 24736741, 2014). "Of interest, these low doses of IGF-1 did not induce hypoglycemia (CO: 151.14 ± 5.73 vs Hz + IGF-I: 143.82 ± 16.71, p = n.s)." (PMID 24161214, 2013). "In these twins with ONA (III:1 and III:2) the hypothalamic-pituitary function seemed normal: growth was regular; no episodes of hypoglycemia had been noted; free T4 levels, IGF1, and cortisol plasma levels were normal; and there was no diabetes insipidus." (PMID 21850183, 2011). "Although NICTH is typically diagnosed with an IGF-2/IGF-1 ratio greater than 10, a ratio below this threshold does not exclude the diagnosis, particularly in the presence of fasting hypoglycemia with suppressed insulin and ketones, findings consistent with IGF-2 mediated effects." (PMID 40727482, 2025). "The “global” impact of fetal hypoglycemia on pancreas growth and function, with both insulin and glucagon concentrations being diminished, were not expected, especially since fetal liver growth and IGF1 secretion were not affected." (PMID 36293384, 2022). "Since IGF-1 is involved in the glucose homeostasis, so this non-significant changes in IGF-1 levels immediately after a 3-side game might be a compensatory mechanism for preventing the post-exercise hypoglycaemia." (PMID 31178752, 2019). "Thus, the relatively high IGF-1 serum levels together with down-regulation of IGFBP in Sub mice, may be a prerequisite to hypoglycemia." (PMID 31707362, 2019). "The crosstalk between IGF-1 and glucagon has seldom been addressed in the literature; indeed, in the early 1990s, acute intravenous infusions of rhIGF-1 in healthy volunteers were reported to impair glucagon excretion and delay recovery after IGF-1-induced hypoglycaemia." (PMID 28881681, 2017). "The usual concern with regards to treatment with IGF-1 has historically been hypoglycaemia, however in the trials done so far it has not always occurred and had been lessened when administered with meals—it was also usually connected to an appearance in a loss of appetite." (PMID 26733412, 2016). "We recorded no hypoglycemia, which indicates that IGF1 shows good toleration in patients." (PMID 24918098, 2014). "Therefore, we believe that IGF-1 is in itself a good predictor of post-load hypoglycemia, irrespective of improvements in liver function." (PMID 24736741, 2014).
Hypoglycemia (continued). "Unlike IGF-1, which lowered blood glucose levels shortly after subcutaneous injection, CV1574-1 injection did not induce hypoglycemia." (PMID 39850478, 2024). "Secondly, individual variability in receptor sensitivity to IGF‐2 might influence the clinical manifestation of hypoglycaemia, independent of the IGF‐2:IGF‐1 ratio." (PMID 38411039, 2024). "When rhIGF-I was infused at a rate achieving plasma IGF-I concentrations close to those observed following rhGH treatment, and yet avoiding the IGF-1-induced hypoglycemia, proteolysis and protein synthesis were not affected, even in the presence of prednisone treatment." (PMID 37764858, 2023). "The precise mechanism of hypoglycemia in SRS and likewise IGF2 dysfunction is not clear to date, but several factors are discussed: IGF2 presumably is able to bind to both IGF1 and IGF2 receptors as well as the insulin receptor and interacts with IGFBP3, possibly influencing glucose homeostasis." (PMID 33922271, 2021).
pancreatic cancer (134 papers, 1990 to 2026). "Similar dependency has been observed in KRAS mutated pancreatic cancer, where IGF1/AKT signaling supports tumor cell survival and dormancy after oncogene ablation." (PMID 41526435, 2026). "In several nested case control studies, nonfasting C-peptide and low circulating IGF binding protein-1 (inhibits IGF-1 activity) were directly related to pancreatic cancer risk." (PMID 30740588, 2018). "Using four PDAC cell lines and two pancreas cancer-associated fibroblasts (CAFs), the expression of insulin-like growth factor-1 (IGF1) and IGF1 receptor (IGF1R) was evaluated by RT-PCR, FACScan, western blot, or ELISA." (PMID 27487118, 2016). "Clinical studies have shown that increased bioavailable IGF-1 levels in serum of pancreatic cancer patients (relative to controls) are associated with accelerated pancreatic cancer death." (PMID 24804677, 2014). "Our results suggest that the loss of AKTs in pancreatic cancer cells may down-regulate membrane cholesterol levels to decrease the responsiveness to IGF-1." (PMID 38920688, 2024). "PDAC has strong invasion and migration ability because under hypoxic conditions, pancreatic cancer-associated fibroblasts (CAFs) are stimulated by hypoxia to produce insulin-like growth Factor 1 (IGF1), and IGF1/IGF1R signaling can stimulate the invasion and migration activity of PDAC cells." (PMID 36187789, 2022). "In addition, TAMs can activate insulin-like growth factor (IGF) receptors on pancreatic cancer cells by secreting IGF-1 and 2, causing pancreatic cancer to resist gemcitabine." (PMID 35668934, 2022). "Indeed, SOCS-1 methylation and downregulation in PDAC-associated CAFs enhance STAT-3-induced IGF-1 expression to promote the survival and proliferation of pancreatic cancer cells." (PMID 33553157, 2020). "IGF-1 is a nutrient-responsive growth factor that activates the inflammatory regulator nuclear factor (NF)-κB, which is linked to many types of cancers, including pancreatic cancer." (PMID 24804677, 2014). "However, on the basis of the results of a subanalysis, it cannot be excluded that a relatively large amount of IGF-1 together with very low levels of IGFBP-3 might still be associated with an increase in pancreatic cancer risk." (PMID 22315049, 2012). "In conclusion, our results generally do not support the hypothesis that circulating levels of IGF-1 and IGFBP-3, or the molar IGF-I/IGFBP-3 ratio are associated with the risk of pancreatic cancer, which confirms the results of most previous prospective studies." (PMID 22315049, 2012). "Studies reported that it promoted the development of pancreatic cancer, renal cancer, and oral cancer by mediating the IGF1 and AKT signaling pathways." (PMID 39314848, 2024). "Lastly, cholesterol metabolism and IGF-1-stimulated growth in pancreatic cancer cells were both regulated by AKT proteins." (PMID 38920688, 2024). "Exogenous IGF-1 has been demonstrated to promote the development of pancreatic cancer cells, underscoring its function as a growth factor in disease progression." (PMID 39087024, 2024). "The two RAS/RAF and PI3K/AKT pathways downstream of IGF-1 are the main pathways involved in the pathogenesis of meningioma, multiple myeloma, pancreatic cancer, and other malignant tumors." (PMID 38032888, 2023). "inhibited the PI3K/Akt signaling pathway by knocking down the IGF-1R gene, thereby inhibiting the proliferation of pancreatic cancer cells and increasing the sensitivity of anticancer drugs, which to some extent proves the role of IGF-1 in pancreatic cancer." (PMID 36755926, 2023). "Autocrine IGF1 signalling has recently been identified as an essential survival mechanism for quiescent cancer cells derived from murine pancreatic tumours, allowing for growth and apoptosis resistance in spite of mutations in KRAS or MYC." (PMID 37608096, 2023). "When treated with an IGF-1 inhibitor, a compensatory insulin receptor (IR) overexpression was observed in pancreatic cancer cells." (PMID 35252207, 2022).
pancreatic cancer (continued). "Biliary IGF-1 perfectly differentiated extrahepatic cholangiocarcinoma from benign biliary abnormalities or pancreatic cancer." (PMID 36389727, 2022). "And the cooperation between Insulin and IGF-1 helps pancreatic cancer resist apoptosis and chemotherapies." (PMID 35252207, 2022). "IGF-1 is a key factor in the development of pancreatic cancer and is known to be subject to dysregulation by several miRNAs, such as miR-486." (PMID 35954223, 2022). "Due to the similar signal pathways activated by Insulin and IGF-1, these two hormones have a similar function in pancreatic cancer." (PMID 35252207, 2022). "In the pancreatic cancer tissue, the tumor-associated fibroblast (TAF) continuously produces IGF-1, which stimulates pancreatic islet beta cells to proliferate and secrete more insulin through a bidirectional microcirculation system in the pancreas." (PMID 35252207, 2022). "The IGF1/IGF-1R signaling axis was also shown to promote the survival of dormant pancreatic cancer cells after oncogenic KRAS or MYC ablation in pancreatic cancer cells." (PMID 33807785, 2021). "Further studies are necessary to assess the contributions of insulin and IGF-1 under experimental settings that more closely reproduce the actual microenvironment present in patients with pancreatic cancer." (PMID 34290274, 2021). "Exogenously added IGF-1 heightened the pancreatic cancer cells’ growth in vitro, and its influence was repressed by the antibody that neutralizes IGF-1." (PMID 33918146, 2021). "For example, the lymphocytic leukemia, NHL, and kidney, lung, oral cavity/pharyngeal, and pancreatic cancer PRS were associated with at least one anthropometric trait and showed directionally consistent associations with HbA1c and IGF-1 levels." (PMID 33579919, 2021). "For instance, in vivo studies have noted that the inhibition of IGF-1/IGF-2 sensitized pancreatic tumors to gemcitabine, whereas combined IGF-1R and CSF-1R inhibition significantly improved survival outcomes in mice with glioblastoma multiforme." (PMID 32512898, 2020). "Pancreatic tumor cells induce expression of insulin-like growth-factor-1 to support cancer cell growth upon contact with fibroblasts." (PMID 33081011, 2020). "In pancreatic cancer, hypoxic conditions both induce IGF-1 expression in cancer-associated fibroblasts (CAFs) and the IGF-1R expression in pancreatic cancer cells, and such IGF-1R signaling promotes cell mobility." (PMID 33511137, 2020). "In turn, Karnevi provided molecular evidence that the decreased anticancer action of metformin in pancreatic cancer cells exposed to HG involved the insulin/insulin-like growth factor-1 (IGF1) pathway." (PMID 30217067, 2018). "The IGF-1/PI3K/PTEN/Akt/NF-кB cascade was introduced as a main process in five pancreatic cancer cell line which was regulated by PTEN." (PMID 29511477, 2017). "AG1024 and I-OMe-AG538, insulin-like growth factor-1 (IGF-1) receptor tyrosine kinase inhibitors, show selective cytotoxicity in starved pancreatic tumor cells to induce necrotic death." (PMID 29053565, 2017). "Animal models of pancreatic cancer fed with metformin showed inhibition of insulin like growth factor-1 (IGF-1) and mTOR, along with an increase in phosphorylated AMPK and tuberous sclerosis complex (TSC1, TSC2)." (PMID 27004404, 2016). "Administration of EP2 and EP4 antagonists significantly inhibited the growth of an orthotopic xenograft of IGF-1-secreting pancreatic cancer cells, with increased phospho-PKC-θ and decreased phospho-ERK." (PMID 25638159, 2015). "A previous study reported that Klotho exerted an inhibitory effect on the IGF-1 pathway in both breast and pancreatic cancer cells." (PMID 25759982, 2015). "In vitro studies have shown that exogenous IGF-1-stimulated growth of pancreatic cancer cell lines is abrogated following treatment with anti-IGF1R antibodies." (PMID 25638159, 2015).
pancreatic cancer (continued). "Instead, we found that insulin and closely related IGF1 promoted cell viability and survival in multiple models of pancreatic cancer progression." (PMID 25373319, 2014). "In those reports, we focused on the impact of CR on reduced pancreatic cancer cell proliferation via decreased serum IGF-1 levels and decreased signaling through the mTOR pathway." (PMID 24804677, 2014). "Silencing the expression of IGF-1R in pancreatic cancer cells inhibits their growth and metastasis and the beneficial effects of calorie restriction in pancreatic cancer models appear mediated through the IGF-1/IGF-1R axis." (PMID 25295009, 2014). "These include treatment with exogenous insulin, increased bioavailability of insulin-like growth factor-1 (IGF-1) combined with increased IGF-1 receptors in pancreatic cancer." (PMID 24879130, 2014). "We have shown that 30% CR significantly decreases incidence of pancreatitis-induced and Kras-induced pancreatic cancer in genetically engineered mouse models (GEMMs), largely through reduction of circulating levels of IGF-1." (PMID 24804677, 2014). "Further studies have documented that IGF-1/IGF-1R-mediated enhanced pancreatic carcinoma proliferation and invasiveness requires an interaction between IGF-1R and the hepatocyte growth receptor c-Met." (PMID 22570653, 2012). "Pancreatic cancer cells have upregulated expression of IGF-1 and IGF-IR that correlate to the aggressiveness of the disease." (PMID 24212642, 2011). "As for pancreatic cancer, the antennepedia protein Antp when coupled to the tumor suppressor p16 successfully inhibited cell growth, and the insulin-like growth factor loop 1 peptide IGF1 is being tried for imaging of early pancreatic tumors." (PMID 21029412, 2010). "Insulin has been reported to increase cell growth in pancreatic cancer cell lines, while IGF1 has been shown to increase pancreatic cancer cell growth." (PMID 17705823, 2007). "It has been shown previously that a variety of growth factors such as FGF-2, EGF, HB-EGF, and IGF-1 are over expressed in pancreatic cancer and that they have the potential to act as mitogens for pancreatic cancer cell lines." (PMID 15817123, 2005). "The activation of the Insulin/IGF-1 pathway promotes pancreatic cancer cell growth." (PMID 41194999, 2025). "In a phase II clinical trial of advanced pancreatic cancer patients treated with IGF1R-directed monoclonal antibody MK-0646 combined with gemcitabine, high expression of IGF1 in the combined treatment group was found to be associated with reduced risk of disease progression or death." (PMID 39394189, 2024). "Additionally, we observed that in the healthy human pancreas, RNA expression of GHR and IGF1 is positively correlated (Spearman correlation coefficient R = 0.43, p < 0.001) and the correlation further increases in pancreatic tumors (R = 0.71, p < 0.001)." (PMID 39000545, 2024). "The changes in IGF-1 concentration observed in pancreatic cancer patients may be attributed to differences in tumor stroma composition and secreted proteins of the IGF axis." (PMID 37373743, 2023). "By stimulating endogenous insulin production, insulin secretagogues increase insulin-like growth factor-1 levels which may promote pancreatic cancer development by interfering with cell metabolism and stimulating cell proliferation." (PMID 37481610, 2023). "On the basis of previous studies, it was thought that the IGF-1/IGFBP-2 ratio could differentiate patients with pancreatic cancer from the control group." (PMID 37373743, 2023). "In pancreatic cancer, differential hydroxymethylation of genes related to pancreas development or function (GATA4, GATA6, PROX1, ONECUT1, MEIS2), and cancer pathogenesis (YAP1, TEAD1, PROX1, IGF1) have also been shown to reliably identify pancreatic cancer from peripheral blood samples." (PMID 36835649, 2023).